CD24 (CD24 molecule)
Diseases named in the same sentence as CD24 in open-access papers (continued):
Sharing a sentence is not in itself a finding about the gene and the disease.
invasive ductal carcinoma (11 papers, 2011 to 2025). "As in the case of CD200 and CD318, the use of CD24 did not include a follow-up to purify differentiated cells, and to date, CD24 plays a role mainly as a cancer stem cell marker for ductal adenocarcinoma." (PMID 36090777, 2022). "Research on the correlation between EGFR expression and CD44/CD24 and their prognostic value in breast invasive ductal carcinoma (BIDC) is limited." (PMID 25429827, 2015). "We studied the correlation between epidermal growth factor receptor (EGFR) and the tumor stem cell markers CD44/CD24 in breast invasive ductal carcinoma (BIDC) and their relationship with prognosis." (PMID 25429827, 2015). "Data presented here are innovative and expand the field in that we measured gene and protein expression of ERα and ERβ, PR IL-6 and IL-8 in uncultured CD49f/CD24 BCSCs from individual human invasive ductal carcinomas." (PMID 25269750, 2014). "We therefore determined the percentage of CD44+/CD24- cells in tissue samples from 147 invasive ductal carcinomas." (PMID 22762532, 2012). "The presence of CD44 and CD24 antigens on invasive ductal carcinoma tissues was analyzed using double-staining immunohistochemistry." (PMID 22762532, 2012). "The prevalence of CD44+/CD24- tumor cells varied greatly in invasive ductal carcinomas, with the occurrence of this phenotype high in primary tumors with high PR status and in secondary tumors." (PMID 22762532, 2012). "CD44+/CD24- phenotype: This phenotype may be an important factor for malignant relapse after surgery and chemotherapy in invasive ductal carcinoma." (PMID 40236653, 2025). "The study presented herein, in contrast, is the first to measure the gene and protein expression of ER and PR in uncultured CD49f/CD24 stem and progenitor sorted cell populations (BCSCs) from freshly isolated benign breast tissue or human invasive ductal carcinomas." (PMID 25269750, 2014). "Thus, the CD44+/CD24- phenotype may be an important factor for malignant relapse following surgical resection and chemotherapy in patients with invasive ductal carcinoma." (PMID 22762532, 2012). "We harvested EV conditioned cell culture media from BT-474 invasive ductal carcinoma cells and MDA-MB-453 metastatic breast carcinoma cells and identified HER2 and CD24 expression by whole-EV ELISA." (PMID 40405296, 2025). "CD24 can also indicate a mammary epithelial origin of BC160 and T47D cells since T47D originates from infiltrating ductal carcinoma and is an epithelial cell line." (PMID 38212739, 2024). "Moreover, the presence of CD44+/CD24-/low tumor cells was associated with a shorter cumulative DFS and OS, suggesting that the CD44+/CD24- phenotype may be an important factor of malignant relapse in patients with surgically resected invasive ductal carcinoma after chemotherapy." (PMID 22762532, 2012). "A total of 147 randomly selected primary and secondary invasive ductal carcinoma samples were assayed for expression of CD44, CD24, ER, PR, and Her2." (PMID 22762532, 2012).
osteosarcoma (11 papers, 2012 to 2025). A usually aggressive malignant bone-forming mesenchymal neoplasm, predominantly affecting adolescents and young adults. "Previous research has shown that CD24 is primarily expressed in tumor cells and promotes osteosarcoma invasion and metastasis." (PMID 38217543, 2024). "CD24 is considered a symbol that affects the progress of osteosarcoma and is related to the prognosis of osteosarcoma." (PMID 38914670, 2024). "In the low TELscore group, TNFSF9 and CD24 were the most active signaling pathways of checkpoints in osteosarcoma cells." (PMID 39980969, 2024). "CHA59, Saos-2, and HuO9 were immunoprobed for the expression of cell surface markers (CD133, CD24, CD166, CD326, CD44, ABCB1, ABCC1, ABCG2) previously reported to be associated with TSCs and/or osteosarcoma." (PMID 22870217, 2012). "Moreover, CD24 regulates cell proliferation, migration, and invasion, e.g., CD24+ cells promote invasion and metastasis in osteosarcoma." (PMID 33919517, 2021). "Therefore, targeting CD24 in osteosarcoma is a promising therapeutic strategy." (PMID 38217543, 2024). "To investigate whether the protection of phagocytosis conferred by downregulating CD24 could be recapitulated in vivo, we treated mice bearing periosteal osteosarcoma with cholesterol-modified Cd24a siRNA or scramble siRNA at a dose of 1 OD every two days through intratumor injection." (PMID 36596773, 2023). "Four ARGs-BRMS, COL4A2, FGF2, and OGT-were used to develop an RFS-predicting model, whereas seven ARGs-CD24, FASN, MMP2, EIF2AK3, ID2, PPARG, and PIK3R3-were used to develop an OS-predicting model in patients with osteosarcoma." (PMID 38217543, 2024). "By the way, CD117, IBSP (Stro-1), ID1, SOX9, CD24, CD44 and THBS-1 were also reported to affect osteosarcoma growth and stemness." (PMID 34828292, 2021). "The research also identified a negative association between CD20+CD24+CD27+ B cells and CD20+IgD+CD38− B cells with osteosarcoma risk." (PMID 39081321, 2024). "There was a negative effect of CD20 on CD24+CD27+ B cells on osteosarcoma based on the IVW (OR: 0.32 [95% CI: 0.14 to 0.72], p = 0.006)." (PMID 39081321, 2024). "Our findings found that CD80 on CD62L+ myeloid dendritic cells and CD28−CD4−CD8− T-cell absolute count are positively associated with OS, and CD20 on CD24+CD27+ B cells and CD20 on IgD+ CD38 B cells have a negative effect on osteosarcoma." (PMID 39081321, 2024). "To investigate the role of CD24 in regulating the macrophage-mediated immune response in OS, we treated bone marrow-derived macrophages (BMDMs) with IL-4 to generate M2-like macrophages and cocultured these less phagocytic macrophages with the GFP+ K7M2 osteosarcoma cell line for 36 h." (PMID 36596773, 2023).
Pleural effusion (11 papers, 2008 to 2023). The presence of an excessive amount of fluid in the pleural cavity. "The isolated cells were sorted within a median time of 8 days after collection of pleural effusion aspirates for cancer stem cell markers CD44+/CD24-/low and ALDH1+." (PMID 28423035, 2017). "Limited by the low cell numbers of some samples, the expression of CD44+CD24-/low was evaluated in 13 out of 18 (72%) pleural effusions." (PMID 28423035, 2017). "Recent work has characterized the cellular heterogeneity of human breast tissues based on cell surface expression of CD44 and CD24, using epithelial cells from primary reduction mammoplasty tissues, pleural effusions, and primary tumors." (PMID 18366788, 2008). "Finally, cell lines that exhibited a spindle-like morphology in culture, were derived from either pleural effusions or primary tumor tissues and were largely comprised of EpCAM-/CD24-/CD49f+ Mesenchymal cells (> 90%); thus, referred to as Mesenchymal lines." (PMID 20964822, 2010). "Expression of CD24 and CD44 on uncultured cells and mammospheres derived from the pleural effusions was documented." (PMID 18541018, 2008). "Using the same CD24 antibody used by Al Hajj and colleagues (ML5) and the same CD44 antibody, we found that only some pleural effusion samples yielded subfractions of cells and these could be detected whether or not the cells were first gated as ESA+ (data not shown)." (PMID 18541018, 2008). "One of the stored pleural effusions, PE14, which formed large mammospheres (average 100 μm) that were highly tumorigenic, showed an unusual phenotype in that all of the cells in the uncultured population were negative for surface expression of CD24 and CD44." (PMID 18541018, 2008).
viral infection (11 papers, 2010 to 2025). "Several genes in this group (CTSG, encoding the neutrophil serin protease Cathepsin G; DEAFA4, defensin alpha 4; LCN2, lipocalin 2; OLFM4, BPI and CD24), are known to be overexpressed in patients with severe viral infections, including COVID-197,14." (PMID 35181735, 2022). "Next, to determine if viral infection would suppress the expression of CD24 on these cells, we performed single-cell RNA-sequencing of infected and uninfected murine epithelial lung cells." (PMID 30770807, 2019). "Having observed that CD24(hi) cells were extensively infected and had decreased ability to proliferate, we then sought to identify the effect of viral infection on cells that are down-stream of CD24-expressing neuronal precursors." (PMID 21249143, 2011). "Given that IFN-I has been shown to play a role in influencing ZIKV infectivity, and it can be a major determinant of tissue specificity for many virus infections, we tested the hypothesis that CD24-low and -high cells differed in antiviral responses." (PMID 36016357, 2022). "We investigated the effect of virus infection on proliferation of CD24(hi) cells." (PMID 21249143, 2011). "Interestingly, we were unable to detect viral infection in cells that expressed CD24 at low levels." (PMID 21249143, 2011). "To document higher replication efficiency of GLV-1h68 strain in sorted CD44+CD24+ESA+ in comparison to CD44+CD24-ESA+ cells, we performed a virus infection followed by a replication assay." (PMID 22901246, 2012). "Given that key mediators of IFN-I signaling are located in the plasma membrane (e.g., IFNAR1, Tyk2), it is possible that CD24 expression alters the composition or structure of key sites within the plasma membrane, which indirectly alters steps in IFN-I responses to virus infections." (PMID 36016357, 2022). "In conclusion, JIMT-1 CD44+/CD24−/low are able at least to a limited extent to respond to exogenous IFN, however they have a dysfunction in initiation of endogenous type I IFN response upon virus infection." (PMID 21079774, 2010). "We sorted CD24 + cells from the lungs of animals: prior to infection (0 DPI), during active infection (2 DPI), and matched populations at 14 days post-infection that had either experienced direct viral infection (14 DPI tdTomato + ) or those that had never been infected (14 DPI tdTomato−)." (PMID 30770807, 2019). "Colocalization analysis of TLR9 and MyD88 to ER or endosomes in JIMT-1 CD44+/CD24−/low CICs showed that neither TLR9 nor MyD88 fully reaches endosomes in 4 h and 6 h respectively, whereas in the CD44−/CD24− non-CIC population localization became endosomal upon virus infection." (PMID 21079774, 2010).
head and neck squamous cell carcinoma (10 papers, 2008 to 2025). A squamous cell carcinoma that arises from any of the following anatomic sites: lip and oral cavity, nasal cavity, paranasal sinuses, pharynx, larynx, and salivary glands. "CD24-positive head and neck squamous cell carcinoma (HNSCC) cell lines maintain a high capacity for self-renewal, exhibit stem-like characteristics, and possess resistance to cisplatin." (PMID 40486886, 2025). "The purpose of this study was to examine the expression of the cancer stem cell markers CD133, CD24, CD44, and CD44 variants, in head and neck squamous cell carcinoma." (PMID 24122205, 2014). "The scope of this study was to study the expression of potential cancer stem cell markers CD133, CD24, and CD44, with focus on CD44 exon variants in head and neck squamous cell carcinoma, in order to find attractive molecular targets for selective cancer targeting." (PMID 24122205, 2014). "CD24+ head and neck squamous cell carcinoma (HNSCC) cell lines were resistant to cisplatin, and this effect was reversed by CD24 inhibition." (PMID 36013184, 2022). "NANOG also plays a role in the self-renewal of CD24+ cancer stem cells in hepatocellular carcinomas and has been found aberrantly expressed in a variety of human cancers, including head and neck squamous cell carcinomas (HNSCC)." (PMID 33233861, 2020). "Similar to CD24, previous studies have identified CD44, BMI1 and ALDH1 as putative markers for CSC in head and neck squamous cell carcinomas." (PMID 24612587, 2014). "Another example would be the upregulation of CD24 in microglial cells and MMP-2 in head and neck squamous cell carcinoma by granulocyte-macrophage colony stimulating factor (CSF2)." (PMID 21359202, 2011). "However, CD24 expression was significantly downregulated in colon adenocarcinoma (COAD), head and neck squamous cell carcinoma (HNSC), kidney renal clear cell carcinoma (KIRC), and thyroid carcinoma (THCA)." (PMID 39791710, 2024). "In head and neck squamous cell carcinoma (HNSCC), however, CSC-enriched populations have been isolated using CD24, CD44, CD133, ALDH1, or CD271 as sorting markers, suggesting that a single common CSC sorting marker may not exist even within identical types of tumor." (PMID 26483189, 2015).
lung adenocarcinoma (10 papers, 2003 to 2025). A carcinoma that arises from the lung and is characterized by the presence of malignant glandular epithelial cells. "BAFF-R expression in IgD+ CD24+ B cells was positively associated with lung adenocarcinoma (LUAD) risk (odds ratio [OR], 1.0168 [95% confidence interval [CI], 1.0006–1.0332]), mediated by macrophage migration inhibition factor (MIF) with a mediation proportion of 14.2% (95% CI, 0.00007–0.0046)." (PMID 41292522, 2025). "A possible correlation between CD24 expression and the well-documented increase in lung adenocarcinoma development in IPF patients is intriguing and remains to be addressed experimentally." (PMID 35053350, 2022). "Previous studies have identified sLeX-modified CD24 as a functional P-selectin ligand that can promote rolling and tumor cell colonization to the lung in lung adenocarcinoma cells." (PMID 31661833, 2019). "Importantly, P-selectin-mediated binding of SCLC to endothelial cells has already been shown in vitro and the CD24/P-selectin pathway was found to initiate lung colonisation of the human lung adenocarcinoma cell line A125 in a mouse model." (PMID 12610508, 2003). "The mRNA expression of CD24, CD47 and CD155 was further verified in colon adenocarcinoma (COAD), liver hepatocellular carcinoma (LIHC), lung adenocarcinoma (LUAD) and stomach adenocarcinoma (STAD) patient samples via cDNA microarray." (PMID 38016957, 2023). "Although CD44 and CD24 were not concluded as the optimal cancer stem cell markers for lung adenocarcinoma cells, CD44+CD24−/lo A549 cells also showed mildly enhanced anchorage-independent in vitro self-renewal." (PMID 35883497, 2022). "There is a negative correlation between NDRG2 expression and CD24 expression in gallbladder carcinoma (GBC), HCC, breast cancer and lung adenocarcinoma." (PMID 26506239, 2016).
Obesity (10 papers, 2015 to 2023). Accumulation of substantial excess body fat. "It is thus of importance to consider gender differences when investigating the associations of CD24 with obesity and weight gain." (PMID 33467499, 2021). "Investigations of the association of CD24 with obesity and weight gain in humans should consider the distribution of the single nucleotide polymorphisms (SNPs) of PPARγ, including gender-dependent associations in this regard." (PMID 33467499, 2021). "Considering the associations documented between CD24 and cancer, we suggest that further investigation of the role of CD24 in insulin sensitivity and weight gain may elucidate associations between cancer and both diabetes and obesity." (PMID 33467499, 2021). "Therefore, investigations of the association between CD24 and obesity and weight gain in humans should consider gender-dependent associations of PPARγ." (PMID 33467499, 2021). "In addition, CD24 has been associated with diabetes, possibly through the associations between cancer, diabetes, and obesity, for which several molecular mechanisms have been proposed, including the insulin synthesis pathway and glucose regulation." (PMID 33467499, 2021). "It is noteworthy that the visceral fat in the obese CD24 KO mice differed not only from that of controls, but also from classical forms of obesity models such as diet-induced obesity." (PMID 33467499, 2021). "Insulin sensitivity, early obesity, and PPARγ expression were assessed in CD24 knockout (KO) mice and compared to wild-type (WT) mice." (PMID 33467499, 2021). "Finally, the possibility of a role for CD24 in insulin sensitivity and obesity, as suggested in this study, may contribute to an improved understanding of the increasingly growing association between cancer and both diabetes and obesity." (PMID 33467499, 2021). "These discoveries highlight the pivotal inhibitory function of the CD24-Siglec-E axis in metabolic dysfunctions and metaflammation, offering a potential immunotherapeutic approach for conditions like obesity, dyslipidemia, insulin resistance, and nonalcoholic steatohepatitis." (PMID 38313430, 2023). "Silencing of the CD24-Siglec-E pathway could deteriorate the diet-induced metabolic disorders, including obesity, dyslipidemia, insulin resistance, and nonalcoholic steatohepatitis (NASH), which could be alleviated by CD24Fc treatment." (PMID 37359556, 2023). "This study provides new insight into the role of CD24 in insulin sensitivity and obesity." (PMID 33467499, 2021). "CD24 KO male mice displayed, at an early age, greater insulin sensitivity and glucose uptake, suggesting a gender-dependent role of CD24 in insulin-sensitive obesity." (PMID 33467499, 2021). "We analyzed the size and structure of WAT in the CD24 knock-out (CD24KO) mouse on the diet-induced-obesity prone C57BL/6 background (C57BL/6N Cd24atm1Pjln) when fed a standard chow diet (chow), high-sucrose/low fat diet (HSD), or high-fat/low sucrose diet (HFD)." (PMID 26536476, 2015). "In addition, Liu also reported that CD24-Siglec-E axis could play key role in obesity-related metabolic dysfunction." (PMID 37359556, 2023). "Finally, CD24 KO male mice may serve as a model of obesity and insulin hyper-sensitivity." (PMID 33467499, 2021). "The effect of the secretome of CAAT isolated from patients with obesity and BC was investigated on the mRNA expression levels of CSC markers, such as CD24 and CD44 as well as EMT markers, such as vimentin and E-cadherin, was investigated in MDA-231 and SUM-149 cells using qRT-PCR." (PMID 35927653, 2022). "Similarly, C57BL/6 mice are known to vary in their response to diet-induced obesity, which in combination with the absence of CD24 increases the variability of the responses." (PMID 26536476, 2015).
renal carcinoma (10 papers, 2012 to 2023). A carcinoma arising from the epithelium of the renal parenchyma or the renal pelvis. "CD24 is frequently overexpressed in different types of cancer, such as ovarian, breast, prostate, bladder, and renal cancer, and is correlated with poor prognosis." (PMID 36737794, 2023). "Beyond that, CD24 was also proposed as a renal cancer biomarker and is discussed as a “hot candidate” for targeted immunotherapy, as it emerged as a novel “don’t eat me”-signal that is expressed on various tumors and prevents their phagocytosis by macrophages." (PMID 36221114, 2022). "This set of data provides further independent indications that VCAM1, EGFR and CD24 are highly expressed in renal cancers and that their high expression is a poor prognostic marker for survival." (PMID 36221114, 2022). "CDl33 +/CD24 + cells with tumor stem cell properties were isolated from the renal carcinoma cells, ACHN and AKI-L, and treated with a Notch pathway inhibitor (MRK-003)." (PMID 35096263, 2022). "Though studies indicate high expression of CD24 and CD44 in renal cancer, more investigations with different experimental approaches are required to examine their importance as CSCs." (PMID 22693526, 2012). "Immunohistochemistry and immunofluorescence analyses for ClC-5, megalin, cubilin, ANXA3, podocalyxin, CD24, CD44, HSA, and LTA marker were performed on 23 kidney biopsies from patients with Lupus Nephritis and 9 control biopsies (obtained from nephrectomies for renal cancer)." (PMID 37594671, 2023).